BDNF (brain derived neurotrophic factor)
Diseases named in the same sentence as BDNF in open-access papers (continued):
Sharing a sentence is not in itself a finding about the gene and the disease.
Anxiety (continued). "One of the most important findings of our study was that NHT reduced anxiety-like behavior as well as blood corticosterone levels, and increased BDNF levels in the hippocampus of mice that were previously exposed to stress (MS+UCMS)." (PMID 24690945, 2014). "In young rats, high cholesterol diet induced less anxiety-like behavior and significantly increased hippocampal BDNF level." (PMID 25179125, 2014). "The effects of potential confounders (total fat intake, age, gender and symptoms of anxiety) were examined using linear regression models (involving log-transformed BDNF values, logBDNF)." (PMID 24593295, 2014). "By blocking BDNF levels in the amygdala, the researchers were able to trigger both anxiety like behaviors and alcohol dependence." (PMID 26501066, 2014). "Chronic social defeat reduced CREB and BDNF levels in the raphe, and increased in parallel anxiety levels." (PMID 25505876, 2014). "Adult rats displayed anxiety-like behavior and accompanied by decreased hippocampal BDNF level after high cholesterol diet treatment." (PMID 25179125, 2014). "Social deprivation stress leads to the development of anxiety in mice, and this appears to be modulated by reductions in BDNF." (PMID 23785661, 2013). "Nonetheless, in rodents peripheral BDNF treatment increased hippocampal neurogenesis and BDNF protein levels, and reduced signs of anxiety in several behavioural tests." (PMID 24019878, 2013). "An important exception in the literature is a strong trend to a decrease in anxiety-related behavior in female mice following forebrain deletion of BDNF." (PMID 24369067, 2013). "Intrahippocampal injections of BDNF in rats lead to an increase in anxiety assessed by facilitatory avoidance and the light–dark test." (PMID 23785661, 2013). "We have reported previously that the combination of a BDNF V/V genotype and early life stress predicts changes in brain structure that are associated with lower HRV and higher anxiety." (PMID 24340091, 2013). "BDNF has been shown to be involved in anxiety-like behaviors in animal models, and numerous types of stressors have been found to cause reduced expression of BDNF." (PMID 23908608, 2013). "Maternal exercise can lead to increased expression of NTs, including VEGF and BDNF, in the PFC of offspring that is associated with decreased anxiety." (PMID 23785661, 2013). "For example, a genetically modified mouse for the brain-derived neurotrophic factor (BDNF) gene shows abnormal secretion of BDNF from neurons and anxiety-like behavior." (PMID 24004567, 2013). "Although we cannot exclude other mechanisms, defect of HTT-dependent BDNF transport and release is likely to contribute to the enhanced anxiety-like phenotype of our mutant." (PMID 24019939, 2013). "Withdrawal from chronic ethanol exposure provoked anxiety-like behaviors, which resulted in reduced BDNF signaling in the CeA and MeA, whereas BDNF infusion into the CeA normalized Arc levels and prevented anxiety-like behaviors." (PMID 23584115, 2012). "Further, two proteins, NGF and BDNF, which are involved in learning and memory performances, ageing-related disorders and anxiety-like behavior, were also analyzed in brain and adrenal gland." (PMID 22808101, 2012). "Various studies have examined how BDNF impacts the interaction between alcohol preference and anxiety." (PMID 23584115, 2012). "This is relevant in light of our results showing that the same time points when stress triggers higher anxiety is also when BDNF is elevated in the BLA." (PMID 22272355, 2012). "Intact hippocampal BDNF signaling determines antidepressant efficacy and influences anxiety-like behaviors." (PMID 21949705, 2011). "The improvement in anxiety alterations corroborated previous studies showing that one molecular mechanism able to modulate these processes was BDNF." (PMID 21985529, 2011).
Anxiety (continued). "In contrast, the combination of the BDNF Val/Val genotype and ELS is associated with increases in amygdala and prefrontal cortex grey matter and with higher anxiety symptoms." (PMID 20141627, 2010). "BDNF is rich in hippocampus and amygdala, and its administrationimproves rat short-term spatial memory and reduces anxiety." (PMID 17502911, 2007). "From this point of view, it is interesting that heterozygous BDNF knockoutmice display unaltered or little anxiety and rather mildalterations in memory, accompanied byaltered hippocampal ACh but unaltered catecholamine levels." (PMID 17502911, 2007). "EE in male mice did not induce anxiety-like behavior, and it was associated with increased hippocampal and pituitary BDNF expression, suggestive of enhanced neurotrophic support." (PMID 41981776, 2026). "Furthermore, HYP also alleviated anxiety-like behaviors and mitigated neuroinflammation by increasing BDNF levels and suppressing microglial activation." (PMID 41696361, 2026). "CUS/UCS protocols (especially those of 10–15-day duration) exhibited the strongest construct and predictive validity, consistently inducing persistent anxiety-like phenotypes, social avoidance, and neuroendocrine changes (e.g., elevated cortisol and altered BDNF, IL-6 expression)." (PMID 40427646, 2025). "Additionally, early weaning has been shown to induce anxiety in mice, potentially through alterations in brain-derived neurotrophic factor (BDNF) signaling pathways." (PMID 41208251, 2025). "The DMM can be given to PHP as it was found to be valid by the experts and feasible to the patients and was also found to be efficient in increasing BDNF levels, reducing anxiety and stress, improve emotional quotient, mental state, quality of life and happiness among hypertensive patients." (PMID 39916293, 2025). "Further, a reduction in expression of the neurotrophin brain-derived neurotrophic factor (BDNF) may lead to mental disorders with anxiety and a decline in learning and memory formation." (PMID 41237192, 2025). "In sum, adult female mice can be responsive to P4 for anti-anxiety/anti-depressant-like behavior; such effects may be independent of NPRs but require 5α-reduction and E2’s priming actions at BDNF in the hippocampus/amygdala complex." (PMID 39940941, 2025). "In the present study, we aimed to perform a comprehensive association analysis of brain-derived neurotrophic factor variants, personality traits, anxiety levels and nicotine use in a group of women and never-smoking controls." (PMID 40806241, 2025). "In summary, these results suggest that activation of the IFN signaling promotes stress-induced anxiety-like behaviors and may serve as a crucial downstream effector of astrocytic BDNF signaling." (PMID 40777598, 2025). "A cluster of DRG atrophy, BDNF, ApoA1, and anxiety correlated best with the diagnosis." (PMID 39909798, 2025). "Collectively, these results reveal that astrocytic BDNF in hippocampal CA1 modulates the susceptibility to stress-induced anxiety-like behaviors, highlighting the importance of interactions between astrocytes and neurons in regulating anxiety sensitivity." (PMID 40777598, 2025). "Conversely, individuals with higher anxiety, who started with lower BDNF, showed a blunted decline." (PMID 41164095, 2025). "Furthermore, MICT can increase the level of BDNF, promotes neurogenesis and improves synaptic connectivity, which can help alleviate anxiety symptoms." (PMID 40008338, 2025). "The dogs with anxiety had a lower concentration of serum BDNF, which could cross the BBB and act as a neurotrophin to promote the expression of rate-limiting enzymes in the 5-HT biosynthesis process." (PMID 40002382, 2025). "However, the relationship between BDNF promoter methylation and anxiety requires further validation to be considered robust." (PMID 40001897, 2025).
Anxiety (continued). "Furthermore, the knockdown of astrocytic BDNF exacerbated anxiety sensitivity and related synaptic abnormalities, potentially through negative regulation of the downstream interferon (IFN) signaling pathway." (PMID 40777598, 2025). "Isochlorogenic acid B improved Pb-induced anxiety by modulating the BDNF signaling pathway." (PMID 39937424, 2025). "In this small longitudinal cohort, winter was associated with a reduction in plasma BDNF in older adults, independent of baseline cognition and anxiety." (PMID 41164095, 2025). "Interestingly, astrocytes displayed noticeable morphological changes under stress-induced anxiety or following knockdown of astrocytic BDNF, suggesting their potential heterogeneity based on morphology." (PMID 40777598, 2025). "In sum, adult female mice can be responsive to P4 for anti-anxiety and anti-depressant behavior, and such effects may be independent of NPRs but require the 5α-reduction and actions of BDNF in the hippocampus of E2." (PMID 39940941, 2025). "While neuronal BDNF has been extensively studied, the role of astrocytic BDNF in modulating stress-induced anxiety sensitivity remains unclear." (PMID 40777598, 2025). "BDNF-TrkB signaling has been implicated in the regulation of stress responses and negative emotion such as anxiety." (PMID 40777598, 2025). "Genetic investigations have further identified conserved risk variants in genes like BDNF and GABRA2, which modulate amygdala reactivity and stress resilience across species, underscoring the evolutionary conservation of anxiety-related neural mechanisms." (PMID 40635883, 2025). "On the basis of the findings presented here, one may propose that the favourable effect of VNS on cognitive performance may be attributed in part to its impact on increasing BDNF levels and ameliorating anxiety." (PMID 40183201, 2025). "Our finding suggests that IFN signaling may act as a mediator between astrocytic BDNF and anxiety sensitivity." (PMID 40777598, 2025). "We aimed to analyze how BDNF impacts antidepressant response, considering the levels of anxiety." (PMID 39408702, 2024). "The main molecular pathways supporting the anti-anxiety effects of RES treatment include the SIRT1/AMPK/CREB/BDNF pathway, which helps restore neurotransmitter balance, improve synaptic plasticity, increase mitochondrial biogenesis, and enhance glucose uptake by neuronal cells." (PMID 39335576, 2024). "Furthermore, prolonged exposure to stress in adolescent rats induced an anxiety-like behavior that was directly correlated to their reduced BDNF protein levels." (PMID 38645426, 2024). "In this study, we specifically measured BDNF levels in the hippocampus and did not assess other central brain regions implicated in anxiety‐like behaviors." (PMID 38988101, 2024). "Elevated expression of mature BDNF (LV-BDNF) increased anxiety and depressive-like behavior at P30." (PMID 39619203, 2024). "Pre-treatment BDNF levels may have predictive value for the antidepressant response in patients taking SSRIs; anxiety symptoms could remain elevated after antidepressant treatment in patients with low basal BDNF levels." (PMID 39408702, 2024). "Based on the discussion of BDNF’s role in anxiety within this article, it is speculated that BDNF is a pivotal target in the anxiety-regulation pathways mediated by gut microbiota." (PMID 39717701, 2024). "On a candidate gene level, BDNF is a promising candidate to be epigenetically studied in relation to fear, anxiety and stress as it plays a pivotal role in brain development, neural plasticity, memory formation and particularly the acquisition, consolidation and extinction of conditioned fear." (PMID 36946487, 2024). "Moreover, low doses (20 and 40 mg/kg) of curcumin decreased the sensitivity of the intestinal tract-produced antidepressant- and anti-anxiety-like effects by elevating serotonin, BDNF and p-CREB levels in the hippocampus in a rat model of IBS." (PMID 38671931, 2024).
Anxiety (continued). "Salivary BDNF influences the hippocampus and enhances anxiety-like behavior." (PMID 39403325, 2024). "BDNF and various brain regions play significant roles in anxiety‐like behaviors in rats." (PMID 38988101, 2024). "The findings support the notion that BDNF alterations may play a role in the neurobiology of panic disorder, potentially contributing to the dysregulation of anxiety‐related behaviors and fear responses." (PMID 38376041, 2024). "Moreover, the precursor of BDNF in the hippocampus has been found to regulate both depressive and anxiety‐like behaviors in rats." (PMID 38988101, 2024). "Additionally, amygdala-specific BDNF knockdown similarly produced anxiety-like behavior, increased energy expenditure, and conferred protection against diet-induced obesity." (PMID 38672441, 2024). "The current study demonstrated that hypothyroidism significantly reduced BDNF levels in the hippocampus of the offspring rats, which may have contributed to the observed increase in anxiety‐like behaviors." (PMID 38988101, 2024). "Interestingly, while sertraline treatment resulted in a reduction in BDNF gene expression, there was still some alleviation of anxiety behavior." (PMID 39595020, 2024). "The decrease in BDNF levels observed in hypothyroidism may be considered a potential mechanism contributing to the elevation of anxiety." (PMID 38988101, 2024). "BDNF levels in the PFC have been found to be lower in rats exposed to prolonged maternal separation, a form of early‐life stress that is associated with increased anxiety‐like behaviors." (PMID 38988101, 2024). "Furthermore, Bifidobacterium longum NCC3001 can normalize anxiety-like behaviors and hippocampal brain-derived neurotrophic factor levels in mice with infectious colitis via the vagal nerve." (PMID 39290561, 2024). "Furthermore, another study has indicated that long-term exposure to cyclophosphamide results in persistent inhibition of BDNF expression and the display of pronounced anxiety-like behaviors, findings that align with what we have previously observed." (PMID 38369521, 2024). "Reduced BDNF levels in these regions may disrupt normal synaptic functioning and impair the regulation of emotional responses, leading to the manifestation of panic attacks." (PMID 38376041, 2024). "The primary outcome variable was the correlation between anxiety scores and serum BDNF levels." (PMID 38907644, 2024). "The concentrated focus was moved to the BDNF, a well-characterized pathological gene of anxiety." (PMID 36936941, 2023). "Sex differences in brain-derived neurotrophic factor (BDNF) and cyclic adenosine monophosphate response element–binding protein (CREB) in the amygdala may also underlie the male long-term anxiety response." (PMID 36633660, 2023). "Therefore, to investigate the molecular mechanism that mediates the produced anxiety-related behaviors, we first measured the mRNA and protein expression levels of BDNF." (PMID 36936941, 2023). "Prior to investigating autism-like social behavioral deficits, we first examined whether BDNF+/Met mice present anxiety-like behavior, which can help us accurately interpret the subsequent social behavioral results." (PMID 37205980, 2023). "It is worth mentioning that in a study by Bahi, it was demonstrated that in rats with an autistic-like phenotype, hippocampal BDNF overexpression attenuates anxiety both in the elevated plus maze test and open field test as well as decreases stereotypy in the marble burying test." (PMID 37239153, 2023). "Upregulation of the BDNF/CREB pathway reportedly suppresses stress-induced anxiety behaviors." (PMID 37663268, 2023). "In one hand, PS results in a decrease in BDNF expression in the hippocampus of rat and on the other hand, it was shown that decreased hippocampal BDNF is involved in anxiety‐like behavior of rats." (PMID 36942730, 2023).
Anxiety (continued). "Burcu Yön in 2019 reported that silymarin supplementation could improve anxiety, learning and memory-related behavior in diabetic rats by increasing BDNF levels." (PMID 37396937, 2023). "Furthermore, BDNF levels were found to be lower in people with anxiety disorders and hypothalamic gene transfer of BDNF reduced anxiety-like behaviors in rodents." (PMID 37926812, 2023). "While BDNF upregulation appears to underlie improved spatial learning in young adult mice, it also seems to promote the development of the anxiety phenotype not observed in middle-aged ES animals." (PMID 35998298, 2023). "Namely, we speculated that BDNF may contribute to the change of the somatic features by improving anxiety symptoms, while somatic symptoms may be served as a core feature in anxiety disorder." (PMID 37533888, 2023). "We therefore hypothesized that BDNF in the vHC plays a role in dampening anxiety-like behaviors and in promoting alcohol-dependent anxiolysis." (PMID 36622381, 2023). "In addition, mice overexpressing a BDNF transgene in the forebrain neurons are characterized by less severe stereotypical behavior in the marble burying test and reduced anxiety-like behavior in the elevated plus maze test." (PMID 37239153, 2023). "Furthermore, bioinformatic analysis revealed that the CREB/BDNF signaling-mediated maintenance of neuronal regeneration, which can prevent anxiety development, was enhanced in WD-fed Tas1r3−/− mice compared with WD-fed WT mice." (PMID 37926812, 2023). "In the amygdala, males are shown to have significant decreases in BDNF and CREB following stress, which are implicated in the anxiety response and could contribute to chronic anxiety following the stress of opioid withdrawal." (PMID 36633660, 2023). "It is unknown how sex interacts with heterozygous mice with diminished activity-dependent BDNF signaling in anxiety." (PMID 37205980, 2023). "Last, although our study lack data on the STAI variable at week 8, it did not affect to discuss of whether baseline serum biomarker (serum BDNF) and anxiety-related variables (PDSS-CV and STAI) could predict the PHQ-15 changes post-escitalopram treatment." (PMID 37533888, 2023). "After controlling for age, gender, education levels (set as a dummy variable), the current duration, comorbid AP, and/or GAD, partial correlation analysis was performed to clarify the correlation between serum BDNF, anxiety-related variables, and PHQ-15 in PD group." (PMID 37533888, 2023). "Reductions in both GFAP and BDNF levels are vital mediators for the advancement of anxiety." (PMID 37273529, 2023). "It has been revealed that BDNF is effective in the regulation of anxiety behavior." (PMID 36942730, 2023). "Several compounds or extracts from natural products, such as darmmarane sapogenins originating from ginseng, tannins from Terminalia chebula fruits, and diterpene quinone Tanshinone IIA isolated from the roots of Salvia miltiorrhiza Bunge, attenuate anxiety by activating the CREB/BDNF pathways." (PMID 37663268, 2023). "Furthermore, it can regulate the transcription and expression of BDNF and induce anxiety-like behavior." (PMID 38075046, 2023). "Reduced BDNF levels promote oxidative stress processes that lead to anxiety." (PMID 36761172, 2022). "The excessive secretion of adrenal hormones and pro-inflammatory cytokines could inhibit the expression of BDNF in the brain, which may accelerate the occurrence of anxiety." (PMID 36358502, 2022). "Meanwhile, greater HGS has been positively associated with hippocampal volume, white matter integrity, and neurocognitive functioning, and resistance training is known to increase BDNF levels, which might prevent anxiety and depressive symptoms." (PMID 35678014, 2022).